FOXO1 (forkhead box O1)
Diseases named in the same sentence as FOXO1 in open-access papers (continued):
Sharing a sentence is not in itself a finding about the gene and the disease.
tumor (continued). "14-3-3 proteins are dysregulated in cancers and can act as either tumor suppressors (14-3-3σ) or oncogenes (14-3-3β, ζ, γ, or θ) by binding and sequestering phosphorylated pro-apoptotic proteins such as BAX, BAD, ASK1, Foxo1 or Foxo3a." (PMID 23236401, 2012). "The most down-regulated genes, FOXO1, FOXN3, and FOXP2, were highly expressed in non-tumor cells, indicating that tumor patients may have an inhibition of the normal cellular function." (PMID 41584858, 2026). "The multimodal treatment strategies for this tumor are based on a specific risk stratification system that not only considers the TNM system, but also histology, fusion status (PAX3 or 7/FOXO1), anatomical site (favorable vs. unfavorable), size, and age." (PMID 41025537, 2026). "Moreover, miR-183 suppresses FOXO1 translation by binding its 3’-UTR, which enhances NSCLC cell proliferation in vitro and tumor growth in vivo." (PMID 41601823, 2026). "Collectively, these results indicate that FOXO1-stimulated G6PD expression in cancer cells can promote their antioxidative capacity, thus reducing apoptosis, increasing proliferation, and enhancing tumor growth under oxidative stress conditions." (PMID 41124013, 2025). "Two distinct methylation‐defined subsets were found for GEMM RMS tumours with no/low Pax3::Foxo1 expression: one subset enriched in Pax7 lineage tumours and a second subset enriched in myogenic factor 5 (Myf5) lineage tumours." (PMID 39812007, 2025). "We concluded that the ML cluster consisted of mouse tumours with high Pax3::Foxo1 expression (11/11, 100%), whereas the MR cluster consisted of mouse tumours with either no or weak Pax3::Foxo1 expression (0/20, 0%) (p < 0.001)." (PMID 39812007, 2025). "In primary localized RMS RT-qPCR showed no tumour-specific fusions (PAX3/7::FOXO1) in cfRNA at baseline, compared to 62% in primary metastatic patients." (PMID 39797974, 2025). "As the MR2 subset contains Pax7 lineage tumours both with and without Pax3::Foxo1 knock‐in, these findings further reinforce the notion that the functional and epigenetic impact of Pax3::Foxo1 in the Pax7 lineage is very limited." (PMID 39812007, 2025). "Amongst these are notable tumor related genes AKT3, CDKN1A, ESR1, FOXO1, TSC2, ERBB3, and NRG4." (PMID 40522948, 2025). "In contrast, RMS tumours in which a Pax3::Foxo1 fusion is directed to the Pax7 lineage do not demonstrate differing methylation from RMS tumours in which other mutations are directed to the Pax7 lineage." (PMID 39812007, 2025). "Overexpression of another quiescent factor, FOXO1, in CAR-T cells enhances stem-like features, characterized by increased mitochondrial activity and improved memory fitness, ultimately leading to the effective tumor control." (PMID 40759740, 2025). "Unlike the xenograft tumors that were treated with a PI3K/mTOR inhibitor, a correlation between tumor biologic behavior and forkhead box O1 immunoreactivity was not present in the patient-derived tumor sections." (PMID 41106249, 2025). "For example, the chemokine CXCL10 promotes the infiltration of T cells into the tumor microenvironment, enhancing anti-tumor immunity, while CCL20 recruits Tregs via the FOXO1/CEBPB/NF-κB signaling pathway, thereby promoting chemotherapy resistance in colorectal cancer." (PMID 41200171, 2025). "However, CD40, glypican 3 (GPC3), Iroquois homeobox 2 (IRX2), FOXO1, EPAS1, and cyclin-dependent kinase inhibitor 1C (CDKN1C) were consistently down-regulated in tumor tissues and GbPDTOs compared to those in normal tissues." (PMID 41376821, 2025).
tumor (continued). "FOXO1 overexpression significantly increased the proportion of CD8+ CAR T cells in the tumours of treated mice at day 12 post-treatment and in both tumours and spleens, wild-type FOXO1-overexpressing CD8+ CAR T cells exhibited a less-differentiated phenotype." (PMID 38600376, 2024). "Suppressing FOXO1 could potentiate the expression of MOMP‐related molecules, potentially fostering the development of anti‐tumour immunity." (PMID 38899748, 2024). "The PI3K/AKT signaling pathway is a pivotal axis for multiple upstream signaling in tumor cells, aggregating and regulating many downstream transcriptional targets, including mTOR (regulates HIF‐1α and c‐Myc on downstream), Forkhead box protein O1 (FoxO1), GSK3, and other key molecules." (PMID 39584783, 2024). "Moreover, we conducted Western blotting analysis to measure the expression of FoxO1 and FBXO22 in xenograft tumours." (PMID 39153212, 2024). "To confirm that FOXO1 overexpression could modify patient CAR T cell phenotype and function in vivo, we treated OVCAR-3 tumour-bearing mice with CAR T cells derived from two of the patients." (PMID 38600376, 2024). "However, the exact mechanisms by which FOXO1 regulates MOMP and inhibits tumour immunotherapy require further detailed investigation." (PMID 38899748, 2024). "Amplification of STK3 led to tumor size suppression and cell apoptosis in ESCC, and the deletion of FOXO1 could reverse the effect." (PMID 38436783, 2024). "Additionally, FOXO1 interacts with pivotal pathways like the PI3K/AKT axis, where dysregulation contributes to tumor progression and therapeutic resistance." (PMID 39201328, 2024). "Additionally, the expression levels of FOXP3, FOXO3, FOXO1, FOXA2, and FOXM1 were found to be elevated in GBM tissues from the TCGA database compared to non-tumor brain tissues, while the level of FOXQ1 was reduced." (PMID 38561331, 2024). "A 50% increase in forkhead box protein O1 (FoxO1), a key regulator of the ubiquitin–proteasome system involved in protein breakdown, was observed in tumor-bearing mice compared to control mice with no tumor." (PMID 37507961, 2023). "Taken together, these data suggest FOXO1 and FOXO3 harbour tumour suppressive qualities in MM." (PMID 37275916, 2023). "From the results, we noticed that tumor cells highly expressed AUP1 significantly correlated with proliferation marker (MCM2, MCM6), PI3K-AKT-MTOR pathway (Akt1, TSC1, mTOR, Foxo1), and autophagy signaling (Atg3, Atg4B, Atg4D, Atg7, Atg9A, Atg16L1) in IDH wildtype tumor cells." (PMID 37029364, 2023). "Age at presentation, tumor invasiveness, and FOXO1 fusion partner were not significantly different between Hispanic and NHW patients." (PMID 37081771, 2023). "FOXO1-negative tumours had a better 5-year relapse-free survival (58.92% versus 44.63%; p = 0.296) with a near-significant correlation in favourable-site tumours (75.10% versus 45.83%; p = 0.063)." (PMID 37138963, 2023). "In the tumor microenvironment, tumor-infiltrating exhausted T cells also express high levels of PD-1, but AP-1 rather than FOXO1 is the major transcription factor involved in the regulation of PD-1 expression." (PMID 37275876, 2023). "Similarly, after their culture with ECs, IL30-overexpressing PCs showed a dramatic upregulation of a wide range of oncogenes, which included CCND2, EGR3, IGFBP5, KLK3, PDLIM4, PTGS1 and SHBG and a few tumor suppressors, such as GPX3, FOXO1, MAX and NKX3-1." (PMID 38087324, 2023). "have shown that microRNA loci are frequently involved in tumor cell proliferation, migration, and invasion and contribute to direct inhibition and MDM2-mediated destabilization of FOXO1, suggesting that FOXO1 inhibition may be interested in HCC development." (PMID 38057816, 2023). "Transplantation of FoxO1–expressing cancer cells after stable knockdown of Atg7 showed no tumor suppressive effect, demonstrating that FoxO1 exerts tumor suppressor activity by inducing autophagic cell death." (PMID 37762548, 2023).
tumor (continued). "Although the published data are not entirely clear, our results show the relevance of FoXO1 in the maintenance of the tumor stem cell phenotype." (PMID 36901916, 2023). "Among them CCNB1, MIF, PLA2G4A may be regarded as oncogenes, whereas RNASE3, APOE, FOXO1, KIT, and EGR1 may be tumor suppressor genes." (PMID 37065484, 2023). "Moreover, the Forkhead box class O (FoxO) family of transcription factors is composed of FoxO1/FKHR, FoxO3/FKHRL1, FoxO4/AFX, and FoxO6, which regulate cellular homeostasis, autophagy, angiogenesis, tumour growth, and metastasis." (PMID 37174088, 2023). "Therefore, in our research, we comprehensively evaluated the importance of ATGs in OV and identified the prognostic signature (namely FOXO1 and CASP8), which was related to tumor immune microenvironment and sensitivity to immunotherapy/ chemotherapy." (PMID 37120633, 2023). "In addition, we previously reported that FOXO1 was the key mediator linking the MAPK and AKT signaling pathways in tumor cells." (PMID 36670097, 2023). "Sex, IRS stage, tumor size, nodal status, primary site, metastatic site, and FOXO1 fusion status (positive or negative) were not significantly different." (PMID 37081771, 2023). "Indeed, another independent research showed that FoXO1 accumulation in BC cells promoted the expression of SOX2, a transcription factor related to the tumor stem cell phenotype." (PMID 36901916, 2023). "To better understand factors that may account for the contrasting tumour suppressor status of FOXO3 and FOXO1 in ALL, we compared RNA-sequencing data from 697 cells transduced with SIN-SIEW-FOXO1, SIN-SIEW-FOXO3 or empty vector." (PMID 36670235, 2023). "Furthermore, forkhead box protein O1 (FOXO1), derived from HCC, not only targets tumor cells but also synchronizes with re-educated macrophages." (PMID 37968714, 2023). "Analysis of Cyld and Foxo1 mRNA expression levels, performed by RT-PCR, globally revealed no relevant differences in peritumor compared to tumor tissues obtained from HF- and LF-HC-fed mice." (PMID 37298191, 2023). "Moreover, FoxO1 stimulates both pro- and anti-inflammatory pathways in macrophages Those data identify FoxO as a major regulator of immune cells which imposes the implication that our findings could reflect the immune processes developing within the tumor tissue." (PMID 36531016, 2022). "However, FoxO1 activated by ERK2 can promote the migratory and invasive potential of tumor cells by inducing EMT, but can also inhibit tumor proliferation." (PMID 33772986, 2022). "In addition, the results of Western blotting suggested a decline in HDAC3 expression in the tumor tissues of CDM-H-treated mice, while FOXO1 acetylation level was increased." (PMID 35126526, 2022). "Intriguingly, we identified copy number alterations (CNAs) of various oncogenes and tumor suppressors (e.g. Yap1, Braf, Foxo1, Akt3 and Rb1) in RMS tumors developing in DK mice, which might play important roles for tumor formation and growth." (PMID 36376321, 2022). "Regarding tumor suppression, JMJD3 could inhibit tumor cell proliferation by regulating vitamin D or enhancing apoptosis through the nuclear translocation of FOXO1 in many cancer types, like colorectal cancer, non-small cell lung cancer or pancreatic cancer." (PMID 35855897, 2022). "FoxO1 expression was limited only in the cytoplasm of metastatic cells in the 4TLM group, and its expression was not determined in the 67NR and tumor-free groups (p ˂ 0.05)." (PMID 36142156, 2022).
tumor (continued). "Previous studies illustrated FOXO1 exhibiting as a tumor suppressor is a vital downstream target of AKT signaling and phosphorylation of FOXO1 by AKT leads to its inactivation after nuclear to cytoplasmic translocation, which results in reducing cell growth ability." (PMID 36002694, 2022). "Similar to in vitro results, animal experiments indicated that miR-9-5p silencing and FOXO1 overexpression could suppress the growth of hepatoma xenografts, while silenced CPEB3 promoted tumor growth in vivo, which was consistent with previous reports for HCC." (PMID 35805200, 2022). "Notably, reversible mitochondrial inhibition yielded durable suppression of tumor proliferation, migration, and invasion via the PI3K/Akt/FoxO1/Cyclin D1 pathway." (PMID 35865479, 2022). "Additionally, CDM inhibited tumor growth in vivo via HDAC3 downregulation and FOXO1 acetylation induction." (PMID 35126526, 2022). "Notably, RT was able to prevent the elevation of some important proteolytic transcriptional factors (p-STAT3, FoXO1, FoXO3) and key proteins in UPS and autophagy pathways, conferring protection against muscle wasting in tumor-bearing mice." (PMID 35847939, 2022). "Finally, we have identified cpd10 as a FOXO1-targeted lead compound and verified that cpd10 treatment of MCL cells elicits a robust cytotoxic response in vitro and suppresses tumor progression in vivo." (PMID 36282572, 2022). "We showed that the expression of both USP7 and EZH2 elevates during tumor progression, corresponding to a diminished FOXO1 expression, and the level of the expression of USP7 and EZH2 strongly correlates with histological grades and prognosis of tumor patients." (PMID 33849069, 2021). "Therefore, both of FOXO1 and FOXO3 proteins are well-known tumor suppressive transcriptional factors involved in many kinds of cellular functions, such as cell cycle arrest and apoptosis." (PMID 34745413, 2021). "FOXO1, a key downstream effector of PTEN, is widely reported as a tumor suppressor in PCa." (PMID 34552661, 2021). "Quantitatively, the tumor vasculature of AMG386‐only or AMG386+SHP099‐treated mice was significantly enriched with FOXO1 compared to control mice, whereas the tumor vasculature of SHP099‐treated mice was not (P = 0.38)." (PMID 34102002, 2021). "Unlike the current speculation that FOXOs can inhibit tumors, our research suggested that FOXO1 activated by DTL could increase the migration and invasion potential of tumor cells by inducing EMT, which exhibits a tumor-promoting effect." (PMID 34635635, 2021). "CDKN1B, FOS, FOXO1, HDAC1, and RB1 were mainly expressed in the nuclear of tumor cells." (PMID 33748162, 2021). "Incorporation of RP11-838N2.4 into exosomes facilitates transfer to parental cells and thus disseminates drug resistance in the tumor microenvironment, and silencing of RP11-838N2.4 via Forkhead box protein O1 (FOXO1) restores drug sensitivity to resistant cells." (PMID 33920605, 2021). "In summary, lncHR1 may inhibit the accumulation of TG in liver cancer cells through the AKT/FoxO1/SREBP-1c pathway and ultimately may reduce the energy supply of cancer cells to inhibit tumor progression." (PMID 34803512, 2021). "In conclusion, this study elucidates a mechanism by which IGF2BP2 promotes DANCR expression and stability through FOXO1 ubiquitination-mediated PID1 expression, thereby promoting cancer cell survival and tumor growth as well as promoting the resistance of GBM cells to etoposide." (PMID 35141227, 2021). "The PAX-FOXO fusion status was determined as a part of the diagnostic procedure through fluorescence in situ hybridization (FISH) examinations (Vysis FOXO1 Break Apart FISH Probe Kit, 03N60-020, Abbott Laboratories) evaluating the signals in at least 100 tumor cells." (PMID 32709151, 2020). "The in vivo results confirmed that MBNL1‐AS1 could block tumor formation of BC by decreasing miR‐135a and inducing PHLPP2/FOXO1." (PMID 31769229, 2020).
tumor (continued). "Then, acetylated FoxO1 binds to ATG7 in the cytosol, leading to ACD and tumor suppression activity." (PMID 32591647, 2020). "As reported in our lifespan studies, haploinsufficiency of the Foxo1 or Foxo3 gene did not affect the lifespans and incidences of neoplasms at death in the AL groups." (PMID 32630045, 2020). "Overexpressing FOXO1 reversed the EMT-like phenotype in vitro and inhibited tumor growth in vivo." (PMID 32708561, 2020). "The relationship between FoxO1 expression and patients' gender, age, as well as tumor size and lymph node metastasis status, was not significant (data not shown)." (PMID 32766159, 2020). "Similarly, lncRNA ASMTL-AS1 serves as a tumor suppressor that inhibits PTC growth and glycolysis by regulating the miR-93-3p/miR-660/FOXO1 axis." (PMID 33197895, 2020). "Additionally, the IHC results further validated the co-localization of FOXO1 and CCL20 in ESCC tumor tissues." (PMID 33052231, 2020). "Hyperactivation of Foxo1 preferentially depletes eTreg cells, which enhances CD8+ T cell function and anti-tumor immunity, suggesting that targeting PI3K/Akt/Foxo pathway in Treg cells could possibly break the Treg cell barrier in anti-tumor therapy." (PMID 31921097, 2019). "For FOXO1 fusion‐negative patients with unfavorable sites, tumor size was the strongest prognostic factor." (PMID 31456361, 2019). "Subsequently, we observed that chemically synthesized cinobufotalin (CB) strongly increased FOXO1-induced DDP chemosensitivity by reducing MYH9 expression, and the reduction in MYH9 modulated GSK3β/β-catenin and its downstream tumor stemness and EMT signal in NPC." (PMID 31754475, 2019). "miR-96 relative expression in tumor tissues was significantly higher than that in non-tumor tissues (P < 0.01), whlie FOXO1 mRNA and protein relative expression was significantly lower in tumor tissues than that in non-tumor tissues (P < 0.01)." (PMID 30828264, 2019). "Several mechanistic details regarding FoxO1 action, for instance, in suppressing tumor cells growth have not been clarified yet, but under most circumstances they seem to involve the Akt pathway which appears critical in clinical specimens." (PMID 30646603, 2019). "Furthermore, signals downstream of WNT/β-catenin, including the TCF4/ZEB1 signal, the tumor stemness pathway, and EMT, were shown to be downregulated in FOXO1-overexpressing NPC cells." (PMID 31754475, 2019). "Importantly, interrupting the TRIB3/AKT1 interaction by a modified α-helix peptide, Pep2–Ae, accelerated FOXO1 degradation, reduced SOX2 accumulation, and decreased the tumor-initiating capacity in MMTV-PyMT and PDX mice." (PMID 31844113, 2019). "Furthermore, we performed multivariate analysis including tumor and UICC stage and the group FOXO1/ pSerine256-FOXO1 IHC." (PMID 30478420, 2018). "In the present study, we compared the expression of RB1 and FOXO1 between SCLs (tumor with monoallelic 13q14 deletion) and SFTs (that without 13q14 deletion), because the number of cases is sufficient for statistical analysis between these tumors." (PMID 28887603, 2018). "In summary, these results suggest that ARHGAP15 might serve as a tumor suppressor during CRC progression and metastasis through PTEN/AKT/FOXO1-signaling pathway." (PMID 29867200, 2018). "FOXO1 and HBP1 may exert their tumor suppression function through the induction of growth arrest and apoptosis." (PMID 28099936, 2017). "FOXO1 was a key effector of PI3K/Akt signaling and functions as tumor suppressors." (PMID 28410203, 2017). "It is thus likely that the myogenic-like transcriptome of ARMS tumours is the result of PAX3:FOXO1 activation rather than a remnant of their lineage origin." (PMID 28615069, 2017). "The first tumor had a deletion of 13q14 that included the RB1 and FOXO1 loci." (PMID 28193293, 2017).